EGFR (epidermal growth factor receptor)
Diseases named in the same sentence as EGFR in open-access papers (continued):
Sharing a sentence is not in itself a finding about the gene and the disease.
cancer (continued). "We showed that epidermal growth factor receptor (EGFR) was downregulated in HPV-positive (HPV+) cancer, and that HPV+ cancer patients exhibited better prognosis than HPV-negative (HPV−) cancer patients." (PMID 34646755, 2021). "Molecular docking results suggested that one of these compounds displaying an anti-cancer activity had a high binding affinity for epidermal growth factor receptor, a known target for cancer treatment." (PMID 34639131, 2021). "cBioPortal was used to investigate the genomic changes of three Nitroglycerin genes (EGFR, HRAS and MAPK3) associated with respective cancers." (PMID 34764329, 2021). "For example, the transcription factors (myc genes), Src-family, epidermal growth factor receptor (EGFR), and Raf kinase have been performed extensive researches in cancer research." (PMID 34512363, 2021). "These bispecific antibodies bridge EGFR on a cancer cell to CD3 on a T cell and induce effective T cell-mediated cancer cell killing." (PMID 33707468, 2021). "All these compounds showed variable anticancer activity against MDA-MB-231, MCF-7, HepG-2 and HCT-116 cancer cell lines and EGFR inhibitory activity comparable to erlotinib." (PMID 33357002, 2021). "FUT8 overexpression is also observed in cancer-associated fibroblasts (CAFs) in non-small-cell lung carcinoma, and FUT8 in CAFs promotes the formation of an invasive and malignant tumor microenvironment via core fucosylation of EGFR." (PMID 34948129, 2021). "Microtubule inhibition therapies increase the sensitivity to EGFR targeting drugs in various cancers." (PMID 33889303, 2021). "Approximately 300 co-clustering phosphosites are verified in patient samples of 5 cancer types or previously implicated in cancer, including CTNNB1 p.S29/Y30, EGFR p.S720, MAPK1 p.S142, and PTPN12 p.S275." (PMID 33875650, 2021). "We also observed that genetic alterations of c-MET/EGFR in CRC co-occurred with other gene alterations and were associated with overexpression of messenger (m)RNA of some cancer hallmark proteins." (PMID 34512327, 2021). "These drugs improve patient survival 6 by targeting receptor tyrosine kinase (RTK) aberrations in cancers, including epidermal growth factor receptor (EGFR), BRAF, anaplastic lymphoma kinase, RET, ROS1, and MET 7,8." (PMID 34405017, 2021). "Recent studies revealed that dual blockade of EGFR/HDAC forcefully inhibited the proliferation of different cancer cell lines." (PMID 34832959, 2021). "The authors evaluated the efficacy of C225 mAbs to target EGFR and improve the internalization, the chemical sensitivity of the cancer cells, and the efficacy of the gold nanoparticles, using different types of EGFR-expressing NSCLC cancer cell lines." (PMID 33981532, 2021). "The second approach used STV and antibody as bridging elements to bind the biotin-modified array on the antibody to the natural epidermal growth factor receptor (EGFR) expressed on certain cancer cells." (PMID 35056239, 2021). "PAP inhibition with drugs such as propranolol or its L and D isomers has been shown to induce EGFR internalization in several cancer cell lines involving increased endocytosis and recycling arrest." (PMID 34298835, 2021). "EGFR is a receptor tyrosine kinase that is frequently upregulated in human cancers, such as in NSCLC." (PMID 34367939, 2021). "Certain cell receptors such as vascular endothelial growth factor (VEGFR) or epidermal growth factor receptor (EGFR) which are overexpressed in cancer cells, offer potential targets for nanotube modifications." (PMID 34330984, 2021). "Unfortunately, the progression of cancer resulting from acquired resistance to EGFR-TKIs is a critical obstacle in the treatment with NSCLC." (PMID 35126111, 2021).
cancer (continued). "Overall, our study highlights a wide-spread reduction in sensitivity to anti-cancer drugs accompanied with an acquired vulnerability to EGFR inhibitors following CDK4/6 inhibitor treatment." (PMID 34944934, 2021). "Further study for the molecular mechanism of GBP5-associated EGFR, STAT1, chemotherapy resistance-associated cancer stemness markers, and PIM1 is warranted in OSCC." (PMID 34439200, 2021). "EGFR participates in many biological processes, such as “MicroRNA in cancer”, “FoxO signaling pathway”, “proteoglycan in cancer” and so on." (PMID 33692692, 2021). "To date, four anti-EGFR antibodies and twelve EGFR TKIs have been approved globally for treatment of various human cancers." (PMID 34207383, 2021). "Utilizing smDIMSA, we uncovered the interaction profile of EGFR with various membrane proteins and demonstrated the promiscuity of these interactions depending on the cancer cell line." (PMID 33603128, 2021). "Its ability to specifically deliver secondary reagents, including chemotherapeutics, therapeutic anti-miRNA and even antibodies to EGFR-positive cancer cells and tumors has been extensively demonstrated by our and other groups." (PMID 34294133, 2021). "Genetic mutations are well known to induce functional abnormalities of cancer-associated proteins, such as EGFR, KRAS and APC, resulting in cancer progression." (PMID 34202873, 2021). "Aberrant expression of PDIA3 is shown to be correlated with poor prognosis in several cancer types and increased cell proliferation mediated by 1,25(OH)2D3 and subsequent activation of the epidermal growth factor receptor (EGFR)." (PMID 33761087, 2021). "Together, these results suggest that TMEM52B suppression promotes cancer cell invasion and survival mainly through EGFR activation and internalization although we cannot completely rule out the possibility that other receptors are involved in TMEM52B function." (PMID 33641663, 2021). "They observed the Cet-Paklitaxel-O-CMC nanoparticles are a promising candidate for the targeted therapy of epidermal growth factor receptor (EGFR) overexpressing cancers." (PMID 34167552, 2021). "Cetuximab (Erbitux) is an anti-EGFR chimeric (mouse/human) monoclonal Ab, which was initially approved for the treatment of certain types of cancers by the FDA in 2004." (PMID 34577541, 2021). "EGFR signalling induces proliferation, which is one of the common events in various types of cancer." (PMID 34205437, 2021). "In recent years, various molecularly targeted drugs have been used alone or in combination with chemotherapy drugs for PDAC treatment, including targeting angiogenic pathways, epidermal growth factor receptors (EGFR), cancer stem cells, and so on." (PMID 34336654, 2021). "Amphiregulin (AREG), which is the ligand for epidermal growth factor receptor (EGFR), plays an important role in wound healing, as well as various aspects of tumorigenesis, metastasis, and angiogenesis in cancer tissue." (PMID 33500443, 2021). "Abnormal expressions of c-MET and EGFR were reported in various human cancers where they support the proliferation and survival of cancer cells." (PMID 34512327, 2021). "The discovery of the connection between mutant epidermal growth factor receptor (EGFR) and cancer cell response to EGFR-tyrosine kinase inhibitors (EGFR-TKIs) that led to development of EGFR-targeted therapy has revolutionized the treatment of NSCLC." (PMID 34368397, 2021). "The Epidermal Growth Factor Receptor (EGFR) signaling pathway is involved in cancer, proliferation, and cell fate determination." (PMID 33990549, 2021). "Targeting the tyrosine kinase domain in wild-type and mutants of the EGFR with small-molecule inhibitors is confirmed as a valid strategy in cancer chemotherapy." (PMID 34771085, 2021). "More directly, EGFR signaling profoundly influences cancer cell metabolism and is involved in the biosynthesis of fatty acids and pyrimidines until glucose catabolism." (PMID 34422883, 2021).
cancer (continued). "This process is frequently deregulated in cancer cells and induces inappropriate activation of the EGFR that drives tumorigenesis." (PMID 33633298, 2021). "Some studies have suggested that nicotine itself has harmful effects and stimulates the expression of some well-known oncogenes, such as epidermal growth factor receptor (EGFR), in cancer cells, which leads to poor prognosis and survival in patients." (PMID 34495991, 2021). "Besides, ARID1A alterations or expression loss could lead to the resistance to EGFR-TKIs via a variety of processes during the tumorigenesis and development of cancers, including epithelial to mesenchymal transition, angiogenesis and the inhibition of apoptosis." (PMID 34715776, 2021). "It has been shown that many cancer cells are characterized by EGFR hyperactivation, gene amplification leading to receptor overexpression, or mutants with dysregulated signaling." (PMID 33572326, 2021). "The expression levels of AREG and EREG ligands are coordinately regulated, and EGFR downstream signaling pathways can be activated by the autocrine/paracrine ligand loop to promote cancer progression." (PMID 34884633, 2021). "This clone inhibited the growth of human EGFR-positive cancer cells transplanted into humanized immunodeficient mice, indicating a possible clinical application of this engineered Bifidobacterium." (PMID 34204302, 2021). "The EGFR L858R and T790M, and BRAF V600E genetic variants are important mutation term features in text mining and are frequently mutated in cancer." (PMID 34759963, 2021). "SPINK1 decreased radiation-induced DNA damage and enhanced radioresistance of cancer cells in EGFR-dependent and nuclear factor erythroid 2–related factor 2–dependent (Nrf2-dependent) manners." (PMID 34747365, 2021). "As demonstrated here, this association is also likely to be dependent upon the pharmacodynamic pathway of afatinib and the overexpression of EGFR in cancer and epithelial cells." (PMID 34221011, 2021). "Dong’s group constructed sulforaphane-functionalized carbon dots (SFN-CDs) for EGFR-overexpressing cancer cell targeted imaging and inhibition." (PMID 34322025, 2021). "The liposome we prepared will have two effects, inhibition of EGFR dimerization hence inhibition of growth of cancer cells, and Dox will have an anti-cancer effect in addition to this." (PMID 33800723, 2021). "Birnbaum et al4 suggested checkpoint inhibitors as neoadjuvant treatment for pancreatic head cancers and anti‐EGFR targeted therapies for pancreatic body/tail cancers." (PMID 33452856, 2021). "The current manuscript presents an overview of the accumulated evidence on HER2- and HER3-targeting therapy and discussion on remaining issues for further improvement of treatments for cancers resistant to EGFR-inhibitors." (PMID 33801379, 2021). "The obtained NPs showed low cytotoxicity, high stability in plasma and an efficient targeting ability towards EGFR-overexpressing cancer cells." (PMID 34683830, 2021). "Inhibition of EGFR endocytosis decreased the proliferation and induced the apoptosis of cancer cells." (PMID 34884765, 2021). "Among these, spironolactone and fenofibrate were also found in the cluster of EGFR inhibitors in Corsello’s pan-cancer UMAP7." (PMID 34907286, 2021). "Our approach was consistently repeated for the conjugation of antibodies against CD44 and EGFR, which are prominent cancer cell markers." (PMID 34959436, 2021). "Signaling from the human epidermal growth factor receptor (HER) family of proteins increases in many cancers, including breast." (PMID 33669586, 2021). "Various well characterized EGFR inhibitors have already been studied and approved for their use in cancer treatment." (PMID 34944593, 2021). "The conjugation of these HS ligands to multivalent fluorescent gold nanoparticles (AuNPs) enabled the specific and efficient targeting of EGFR-overexpressed cancer cells." (PMID 34163672, 2021).
cancer (continued). "Using smDIMSA, we revealed the transient interaction profile of EGFR in various cancer cell lines, which demonstrated an unprecedented level of promiscuity in its interactions in a manner dependent on the cell line." (PMID 33603128, 2021). "Studies have shown that the overexpression of the epidermal growth factor receptor (EGFR), a member of the ErbB family of receptors, was associated with the development of various cancers." (PMID 34360933, 2021). "Instead, we found that combined FGFRi and Akti or PI3K-mTORi exhibited much stronger and superior inhibition of cancer cell growth compared to combined FGFRi and EGFR-TKI across all the erlotinib, gefitinib-, and osimertinib-resistant models." (PMID 34267282, 2021). "These biomolecules are small (58 amino acids) engineered proteins that can be selected to bind with a nanomolar affinity a large variety of cancer-associated molecular targets including HER2, EGFR, VEGFR2, PD-L1, etc.." (PMID 34201280, 2021). "The activation of angiogenesis can occur by EGFR up-regulation, a process involved in cancer metastasis and migration to the distant sites." (PMID 34943856, 2021). "Epidermal growth factor (EGF)-nanoparticle conjugates have the potential for cancer therapeutics due to the unique cytotoxic activity in cancer cells with EGF receptor (EGFR) overexpression." (PMID 34512175, 2021). "Previous studies have shown that excessive activation of EGFR signaling can promote pathogenesis of different cancers, while its target genes such as c-myc, c-fos, and c-jun, are known to be proto-oncogenes." (PMID 34830467, 2021). "This novel EGFR-targeting enzymatic prodrug system, Fcy–hEGF/5-FC, displayed potential to be a potent inhibitor for treatment of EGFR-overexpressing cancers, while reducing the severe side effects of 5-FU." (PMID 33672989, 2021). "For example, TMEM16A and EGFR can forming a functional complex to regulate cancer cell proliferation." (PMID 33935737, 2021). "The in vitro studies proffered evidence that under hypoxia condition, EGFL6 binds to EGFR, activates EGFR/αvβ3 integrin receptors to affect cancer cell proliferation." (PMID 33726836, 2021). "Parts of the work were previously presented at the German Pharm-Tox Summit (Göttingen, 2017): Hafner S, Lang S, Syrovets T, Simmet T: Anti-Cancer Efficacy of the Cardenolide Glycoside Acovenoside A is Mediated by EGFR Arrest." (PMID 34025398, 2021). "Several studies report that in different cancer cell lines the -216T/T genotype of the EGFR promoter leads to the highest EGFR expression and the -216G/G genotype to the lowest with the -216 G/T genotype being in between." (PMID 34168192, 2021). "Several studies have identified that cancer cells use EGFR signaling to stabilize PD-L1 expression for escaping T-cell immunity." (PMID 34639141, 2021). "Activating cancer driver events in the EGFR gene are the most frequently found kinase alterations in GBMs, yet early studies of EGFR inhibitor therapy did not yield clinical benefit." (PMID 33525329, 2021). "Amplified or over-activated EGFR represses autophagy for growth, survival, and chemotherapy resistance in many cancers." (PMID 34830108, 2021). "Combining the detection of EGFR and KRAS mutations in ctDNA with the detection of protein biomarkers increased cancer detection sensitivity to 74.7% (65/87)." (PMID 33442424, 2021). "The EGFR molecules expressed over cancer cells and the correspondingly larger anti-EGFR antibody-conjugated GNR attached to EFG receptors." (PMID 34361251, 2021). "The antibiotic monensin is known to inhibit the exit of internalized EGFR from sorting endosomes and prevents EGFR recycling, which was shown to induce apoptosis in cancer cells." (PMID 34025398, 2021). "The EGFR (ErbB) family members are central transducers of a myriad of cellular signaling cascades that drive cancer progression." (PMID 34074257, 2021).
cancer (continued). "To further examine the relationship between 14-3-3σ and EGFR in human cancers, we analyzed the levels of 14-3-3σ and EGFR by IHC in serial sections of HCC samples." (PMID 33391517, 2021). "Photosensitizer ICG and chemotherapy drug CUR were coencapsulated into the liposomes, whose surface was further modified with GE11 peptides (GE11-CUR/ICG-LPs), to endow it with active targeting effects toward EGFR-positive-expressed cancer cells." (PMID 33868396, 2021). "Our recent work has demonstrated that one of the mTOR complexes, mTORC2, is a strong acetylation driver in cancer cells, especially in the context of EGFR-mutant genotypes." (PMID 33916219, 2021). "Together, these results provide a rationale for exploring the potential of targeting the EGFR–CBL–CIN85 axis in CBL-inactivated mutant cancers." (PMID 33627783, 2021). "EGFR has at least one drug that has been developed for the cancer type in which the target was identified as a priority." (PMID 33968733, 2021). "This is in contrast to monotherapies, such as anti-EGFR, which are suggested to target only certain parts of the cancer networks." (PMID 34638492, 2021). "Epidermal growth factor receptor (EGFR), as one of the most critical anti-cancer targets belonging to the receptor tyrosine kinase family, represents a quintessential example." (PMID 34070173, 2021). "EGFR is an excellent candidate for targeted cancer therapy, being over-expressed in many types of cancers, including CRC." (PMID 34638601, 2021). "In the cancer context, it has been shown that AnxA1 promotes the stabilization and the constitutive activation of EGFR, as well as the nuclear localization of this receptor." (PMID 34571894, 2021). "In numerous cancers, therapies targeting various EGFR signaling cascade components are increasingly being used in EGFR expressing cancers (esp." (PMID 34539578, 2021). "It is known from the literature that S1P regulates EGFR expression in cancer as well in non-cancer cells, and we recently demonstrated the existence of a cross-talk between S1P and EGFR signaling pathways in the regulation of human GBM cell invasiveness." (PMID 34201962, 2021). "Epidermal Growth Factor Receptor (EGFR) is an attractive target in cancer therapy due to its involvement in cell proliferation and differentiation." (PMID 34577570, 2021). "We map co-resistance ranks in multiple drug pairs and identified a more widespread occurrence of co-resistance to the EGFR-tyrosine kinase inhibitor (TKI) gefitinib in hundreds of cancer cell lines resistant to at least 11 AMDs." (PMID 33850249, 2021). "Cancer cells that are resistant to cetuximab, a monoclonal antibody that binds to EGFR, express high levels of nEGFR and Src family kinase (SFK)." (PMID 34884765, 2021). "Cetuximab is a chimeric human-murine monoclonal antibody that targets the epidermal growth factor receptor and has been used against various cancers in clinical trials." (PMID 34715860, 2021). "For example, imprinting of Epidermal Growth Factor Receptor (EGFR) epitopes (which are overexpressed in cancer cells) can be accomplished using N-isopropylacrylamide (NIPAm) based molecules." (PMID 34615526, 2021). "Several resistance mechanisms for EGFR-inhibitors have been elucidated; HER2 and HER3 contribute to the induction of resistance to EGFR inhibitors in certain cancers." (PMID 33801379, 2021). "The activation of EGFR in cancer cells is known to induce the activation of extracellular-regulated kinase (ERK) or Akt (protein kinase B; PKB) signaling pathways." (PMID 34869748, 2021).